HGF (hepatocyte growth factor)
Diseases named in the same sentence as HGF in open-access papers (continued):
Sharing a sentence is not in itself a finding about the gene and the disease.
COVID-19 (92 papers, 2020 to 2025). A disease caused by infection with severe acute respiratory syndrome coronavirus 2. "Studies on HGF have shown that HGF is associated with severe COVID-19 and can predict the severity and mortality of patients with COVID-1940,41." (PMID 38710800, 2024). "In line with previous research, high PD-L1 and HGF plasma levels were associated with COVID-19 severity." (PMID 36351919, 2022). "Mild COVID-19 patients had significantly high pGSN/IL-6 amongst all the multi-analyte markers following day 4 of symptoms onset compared with moderate and severe COVID-19 patients, and pGSN/IP-10 and pGSN/HGF showed a trend toward this association." (PMID 36148234, 2022). "HGF, IL-1α, and IL 27 at hospital admission were strongly associated with severe/critical COVID-19 patients and therefore are excellent predictors of bad prognosis." (PMID 34066892, 2021). "Of these age-correlated proteins, six had been also associated with COVID-19 severity: HGF and CXCL9 shown the highest coefficients while IL10RB, VEGFA, IL-6 and TNF showed low albeit significant correlation (r < 0.30)." (PMID 34335580, 2021). "In conclusion, the present study provides insights in the early pathophysiological events associated with severe COVID-19 and identified HGF and CXCL13 as critical pathogenic biomarkers of disease severity and best predictors of ICU admission and death." (PMID 34373466, 2021). "Our finding is consistent with other recent studies showing the association of HGF with COVID-19 severity." (PMID 33239683, 2020). "In particular, we found an association between plasma proteins elevated in severe COVID-19, such as HGF, AREG, CKAP4, S100A12, NCF2, ITGB6, and a subpopulation of monocytes with lower expression of CD86 and HLA-DR, which are characteristics of myeloid-derived suppressor-like cells." (PMID 36829233, 2023). "HGF has been linked to a neutrophil signature that predicts critically ill COVID-19 patients." (PMID 34335580, 2021). "However, our data suggest that acute neurological dysfunction in COVID-19 is also associated with a different repertoire of cytokine responses, with HGF and IL-12p40 showing the statistically most robust discrimination between participants with and without an abnormal GCS." (PMID 38135686, 2023). "This may underlie our observation that HGF was inversely regulated with D-dimers and IL-6 and might reflect the coordinated sequelae of tissue injury and healing processes in severely affected COVID-19 patients." (PMID 37834869, 2023). "After analyzing 45 cytokines in the plasma of COVID-19 patients, we found that only the levels of IP-10, HGF, and IL-18 were significantly higher in COVID-19 patients compared to healthy and/or recovered subjects." (PMID 38486975, 2024). "The combined increased levels of CXCL13 and HGF were shown in a large Swiss study to be the best predictor of COVID-19 admission to the intensive care unit (ICU)." (PMID 39767799, 2024). "We identified a remarkably strong pro-inflammatory cytokine/chemokine profile with high levels for sCD163, CCL20, HGF, CHintinase3like1 and Pentraxin3 in serum which correlated with COVID-19 disease severity and overall outcome." (PMID 38839796, 2024). "We also found that plasma HGF levels were significantly higher in COVID-19 patients than in recovered (P < 0.001) and healthy (P < 0.05) subjects." (PMID 38486975, 2024). "The combination HGF/CXCL13 was the best predictor for ICU-admission but also fatal outcome in 3 combined independent cohorts of COVID-19 patients." (PMID 38839796, 2024). "As all COVID-19 patients in our study were hospitalized, it is reasonable to consider IP-10, HGF, and IL-18 as biomarkers of disease severity in SARS-CoV-2 infected patients." (PMID 38486975, 2024). "Studies have shown that COVID-19 patients with severe respiratory symptoms have significantly lower levels of HGF in their blood and that treatment with HGF can reduce lung inflammation and prevent the progression of COVID-19-related lung injury." (PMID 39040605, 2024).
COVID-19 (continued). "Concentrations of IP-10 and HGF were statistically higher in blood plasma of COVID-19 patients compared to recovered (P < 0.0001) and healthy (P < 0.05 and P < 0.001) subjects." (PMID 38486975, 2024). "Statistically significantly higher levels of HGF were detected in the plasma of COVID-19 patients compared to healthy (P < 0.05) and recovered (P < 0.001) subjects." (PMID 38486975, 2024). "We found significantly increased levels of interferon γ-induced protein 10 kDa, hepatocyte growth factor, and interleukin-18 in the plasma of COVID-19 patients." (PMID 38486975, 2024). "The increased serum level of HGF, in addition to other analytes, as a marker of COVID-19 severity, was also reported in other studies, although these were conducted using a small number of patients." (PMID 36902351, 2023). "Among those, HGF, IL-1β and fibrinogen showed significant differences in the group of moderate COVID-19 cases." (PMID 37388734, 2023). "Some cytokines, such as hepatocyte growth factor (HGF), play an important role in the severity of COVID-19." (PMID 38049886, 2023). "Three cytokines/chemokines, IL-6, CXCL-10, and HGF, were found to be highly elevated in plasma samples of severe COVID-19 patients compared to mild/moderate patients." (PMID 37685858, 2023). "However, until now, the role of HGF in coagulation risk in post-COVID-19 patients is unknown, and how it correlates with D-dimer as a coagulation factor and interleukin 6 as a proinflammatory cytokine that can induce coagulation, especially due to long-term cytokine storms." (PMID 37504277, 2023). "Currently, there is no information on the effect of SARS-CoV-2 infection on serum hepatocyte growth factor (HGF) concentrations as a marker of the prognosis of coagulation in long COVID-19 survivors." (PMID 37504277, 2023). "Currently, there is no information on the effect of SARS-CoV-2 infection on serum HGF concentrations as a marker of the prognosis of coagulation in long COVID-19 survivors." (PMID 37504277, 2023). "This dynamic of protein levels in acute and convalescent phase was specific to KRT19 and HGF, as most proteins upregulated in severe COVID-19 during acute phase normalized during convalescence." (PMID 36829233, 2023). "We first observed a significantly elevated level of 7 serum cytokines (IL-1Ra, IL-2, IL-3, IL-10, IL-12p40, CXCL10, and HGF) in all COVID-19 cases when compared with controls." (PMID 35386707, 2022). "COVID-19 patients showed higher levels of pro-inflammatory cytokines, such as IP-10 IL-15,IL-1RA NT-proBNP, and the angiogenic growth factor HGF, among others." (PMID 35844615, 2022). "In this subgroup of patients with COVID-19, we also observed higher IL-8 levels on the 10th day accompanied by high HGF values compared to those in healthy controls." (PMID 35372407, 2022). "HGF promotes alveolar epithelial and endothelial repair after acute lung injury and was reported to be significantly upregulated in COVID-19 patients." (PMID 36405747, 2022). "COVID-19 patients, in comparison to healthy controls, showed six elevated biomarkers (IP-10, NT-proBNP, HGF, MCP-3, IL-15, IL-1RA)." (PMID 35844615, 2022). "As shown in previous studies, COVID-19 is characterized by the upregulation of pro-inflammatory cytokines which was evident in our study with the upregulation of IL-6, IP-10, M-CSF, HGF, CTAK and TGF-b1." (PMID 36148234, 2022). "We observed that COVID-19 patients with increased levels of pGSN/IL-6, pGSN/HGF and pGSN/IgM compared with the other markers are more likely not to progress to severe disease and will eventually be discharged alive." (PMID 36148234, 2022). "Meanwhile, combining pGSN with IL-6 (AUC=0.904; p=0.003) showed a more significant ability to predict mild COVID-19 and IP-10 (AUC=0.754; p=0.065), HGF (AUC=0.746; p=0.075) and TGF-β1 (AUC=0.765; p=0.078) demonstrated a trend toward significance." (PMID 36148234, 2022).
COVID-19 (continued). "Patients who died from COVID-19 also presented with elevated Ang-2 and HGF levels, accompanied by low concentrations of TIMP-2." (PMID 35372407, 2022). "Univariate analyses were carried out, and 6 cytokines including G-CSF, HGF, IL-10, IL-18, M-CSF and SCGF-β were found to be associated with the severity of COVID-19." (PMID 34489933, 2021). "In two studies, conducted on a small number (n = 4912 and n = 4013) of patients, HGF in addition to other markers was proposed to serve as a marker of severity of COVID-19." (PMID 34373466, 2021). "Here the authors demonstrate the association of HGF and CXCL13 production with increased severity and mortality in COVID-19 patients." (PMID 34373466, 2021). "There is also the possibility that HGF is indirectly related to the pathophysiology of liver dysfunction and the cytokine storm in the severe cases of COVID-19." (PMID 34830714, 2021). "In the other direction, we found liability to COVID-19 was inversely associated with several cytokines, such as GCSF and HGF." (PMID 34163532, 2021). "HGF plays a critical role in tissue repair and regeneration, particularly in the liver and lungs, and has been found to have potential therapeutic effects in COVID-19 due to its ability to reduce lung injury and improve pulmonary function." (PMID 39040605, 2024). "Moreover, we found incrementing expression of monocyte chemotactic protein-3 (MCP-3) and hepatocyte growth factor (HGF) when comparing moderate to severe COVID-19." (PMID 39767799, 2024). "Thus, our results showed that COVID-19 significantly increases the levels of IP-10, HGF, and IL-18 in the plasma of COVID-19 patients compared to healthy and/or recovered individuals." (PMID 38486975, 2024). "This review discusses the pathophysiology between COVID-19 and HGF, IL-6, and D-dimer." (PMID 37504277, 2023). "This is in line with a previous report implicating HGF in COVID-19 disease severity." (PMID 36829233, 2023). "Interestingly, a set of six proteins had a similar behavior to KRT19 and HGF during the acute phase of COVID-19, except that they reached healthy levels during convalescence." (PMID 36829233, 2023). "Consistent with this view, more than 90% of non-ICU patients with moderate respiratory syndrome have low HGF levels, thus identifying HGF as one of the critical pathogenic biomarkers for disease severity and the best predictor of the risk of ICU admission and death in COVID-19 sufferers." (PMID 37504277, 2023). "Importantly, the severe cases of COVID-19 investigated in the present study associated a major increase in the CRP and MCP-1 serum levels assisted by enhanced suPAR, sTREM-1 and HGF values." (PMID 37388734, 2023). "Similarly, hepatocyte growth factor (HGF), a protein involved in tissue regeneration after damage, had higher levels in severe COVID-19 during acute phase that persisted during convalescence, indicating its release during tissue repair." (PMID 36829233, 2023). "Interestingly, just one (HGF) was found to be dysregulated between severe and moderate COVID-19 patients in both men and women." (PMID 35844615, 2022). "The data then suggest that it is a macromolecule that may be related to the development of symptoms in COVID-19 or that its elevation is due to some counterregulatory mechanism and that, like HGF, it can be used as a biomarker of severity." (PMID 36163447, 2022). "Additionally, M-CSF and HGF are proposed to be involved in the major biological processes of severe COVID-19, mirroring the level of systemic hyperinflammatory state." (PMID 34067072, 2021). "Our study suggests that COPD patients have a systemic dysregulation in chemokine networks (including HGF and CXCL9) that could make them more susceptible to severe COVID-19." (PMID 34335580, 2021). "In this setting, our data support that HGF and OPG could be involved in severe COVID-19 by affecting pathways implicated in coagulopathy and thrombosis." (PMID 34335580, 2021).
COVID-19 (continued). "HGF also has antiapoptotic effect against proinflammatory stimuli towards epithelial cells, which is important as an angiogenic and a recovery agent for COVID-19 patients." (PMID 34306612, 2021). "Previous studies reported that COVID-19 is frequently associated with a massive production of 14 cytokines including IFN-γ, IL-1RA (IL1RN), IL-2RA, IL-6, IL-10, IL-18, HGF, MCP-3 (CCL7), MIG (CXCL9), M-CSF (CSF1), G-CSF (CSF3), MIG-1a (CCL3), CTACK (CCL27), and IP-10 (CXCL10)." (PMID 34262555, 2021). "Similarly, the levels of HGF highly correlated with MT-CYTB in COVID-19 (r = 0.47, 95% CI 0.29–0.62, P < 0.0001, n = 94)." (PMID 33444289, 2021). "Thus, the observed interactions may suggest a protective role for HGF in ameliorating the progression of COVID-19, as well as a target for drug research." (PMID 39040605, 2024). "Thus, it could be relevant to prospectively monitor KRT19 and HGF in COVID-19, to evaluate their potential value in prognosis of lung impairment post-COVID-19." (PMID 36829233, 2023). "Nonetheless, the role of HGF as a biomarker for coagulation in survivors of COVID-19 is unknown." (PMID 37504277, 2023). "Its reduced levels correlated with elevated levels of thrombosis markers (D-dimer), acute phase reactants (ferritin), and inflammatory modulators (HGF and IP-10), suggesting that strategies that increase citric acid levels could be protective for COVID-19 infected patients." (PMID 35844615, 2022). "Our findings suggest that high HGF levels at 9 weeks post–COVID-19 could indicate ongoing alveolar repair proportionate to the degree of acute lung injury; however, further studies are needed to determine the effect of HGF on COVID-19 recovery." (PMID 34111030, 2021). "For this reason, through this cytokine profile in ABO blood groups, we could find HGF as a bad prognosis biomarker in all COVID-19 patients (both ABO groups), growing up to 17 times more intubation or death risk in non-O patients with persistently higher levels." (PMID 34721388, 2021). "Based on our results, we suggest that measuring levels of HGF, CXCL9, IL10-RB, MCP-3 and EN-RAGE could be further evaluated in larger cohorts as biomarkers of a “pre-morbid state” for the susceptibility to severe COVID-19." (PMID 34335580, 2021). "As expected, plasma concentrations of several inflammatory mediators, including IL-1α, IL-6, IL-18, IP-10, HGF, MCP-3, and M-CSF, were elevated in patients with acute COVID-19, especially those with severe disease." (PMID 39847442, 2025). "We found the combination of the following factors to be of most interest to follow up on in a larger cohort of post-COVID-19 patients: CXCL13, DCN, HGF, MCP-3 and TNFRSF12A." (PMID 39767799, 2024). "Markers found to be significantly elevated in COVID-19 compared to control samples included CCL19, CXCL-13, MCP-3, PGF, HGF and TNF." (PMID 39767799, 2024). "HGF and CXCL13 were also previously identified as markers of severe COVID-19 and good predictors of ICU admission." (PMID 38839796, 2024). "Of interest, DCN and TNFRSF12A were distinctly elevated in severe COVID-19, separating severe disease from moderate, while MCP-3 and HGF were found to increment with disease severity." (PMID 39767799, 2024). "Our approach also relies on controlled delivery of hepatocyte regenerative stimuli, HGF and EGF, to the liver using mRNA-LNP23,24, which has been validated as clinically safe with the recent mRNA-based COVID-19 vaccines." (PMID 38866762, 2024). "Specifically, IP-10, sTNF-R1, sTNF-R2, sCD30, sCD163, HGF, SCYB16, IL-16, MIG, SDF-1, and fractalkine were found to be major components of the COVID-19 cytokine storm." (PMID 38476443, 2024). "MCP-3 and HGF were significantly increased (>1 NPX mean difference) in all patient groups, incrementing from healthy to moderate to severe COVID-19." (PMID 39767799, 2024).
COVID-19 (continued). "In patients with severe COVID-19, anti-SARS-CoV-2 antibodies and pro-inflammatory cytokines and chemokines (IL-6, CXCL-10, and HGF) were significantly elevated." (PMID 39063142, 2024). "Six cytokines and chemokines, IL-10, IP-10, HGF, SCGF-β, IL-16, and IL-18, were identified for analysing the progression patterns of COVID-19, especially IP-10, which was closely correlated with SOFA scores." (PMID 38710800, 2024). "Analysis of cytokine profiles showed increased plasma levels of IP-10, HGF, VEGF-A, IL-7, IL-18, and MCP-1/CCL2 in COVID-19 patients." (PMID 38486975, 2024). "Subgroup analyses of the five deceased COVID-19 patients (all males) revealed significantly upregulated proteins such as CD8A, SLAMF1 and LIF-R, HGF, CCL25, NT3 compared to the surviving patients." (PMID 37832397, 2023). "Among 48 cytokines/chemokines, evaluated by multiplex analysis in patient plasma, 6 (IL-6, CXCL-10, HGF, MIG, MCP-1, and G-CSF) were identified as highly significant in COVID-19 patients compared to non-COVID-19 respiratory disease controls (p-value < 0.0001)." (PMID 37685858, 2023). "The receiver operating characteristic (ROC) analysis demonstrated that the following chemokines: MIP-1α, IP-10, and MIG, and the following GFs: basic-FGF, HGF, SCGF-β, G- CSF, M-CSF, and MIF can be useful parameters for diagnosing COVID-19 patients." (PMID 38239363, 2023). "The study demonstrated that serum levels of MIP-1α, RANTES, Eotaxin, CTACK, GRO-α, IP-10, MIG, basic-FGF, HGF, SCGF-β, G-CSF, M-CSF, SCF, MIF, LIF, and TRAIL were significant higher in COVID-19 patients than in the control group." (PMID 38239363, 2023). "Severe COVID-19 patients had elevated levels of cytokines, IL-6, CXCL-10, and HGF compared to mild/moderate." (PMID 37685858, 2023). "A more stringent analysis of median-centred cytokine data (which corrected for between participant skewing of mediator levels) confirmed that HGF and IL-12p40 were higher in the abnormal GCS COVID-19 participants, and correlated with cognate NfL levels." (PMID 38135686, 2023). "In that regard, HGF was found to predict disease severity (i.e., ICU admission) and mortality in COVID-19 patients." (PMID 37834869, 2023). "Inflammatory cytokines (IL-6, IP-10, HGF, M-CSF and CTAK) as well as pGSN were elevated in severe COVID-19 patients reminiscent of reported cytokine storms that are highly associated with increased organ damage." (PMID 36148234, 2022). "We have shown that, among the 49 soluble mediators measured, two cytokines, HGF and CXCL13, are the best predictors of the need for ICU hospitalization for COVID-19 patients." (PMID 34373466, 2021). "Since HGF is increased in chronic inflammatory diseases, further studies are needed to establish whether this protein is elevated in severe COVID-19 because a pre-condition related to the comorbidity, or it increases during the infection and is involved in the pathophysiology of severe COVID-19." (PMID 34335580, 2021). "We have identified two cytokines, i.e., HGF and CXCL13, as the best immunological signature predicting the severity of COVID-19 requiring ICU admission." (PMID 34373466, 2021). "In summary, several proteins in plasma that are increased in severe COVID-19 patients, such as IL-6, IL-8, IL-18, MCP-1, OPG, and HGF, are more abundant in healthy elderly compared to young individuals." (PMID 34434199, 2021). "HGF frequently counteracts TGFB1, another cytokine involved in apoptosis, and expressed at elevated levels in COVID-19 patients." (PMID 33239683, 2020). "In this context, we also found increased numbers of cMet+ T cells in the COVID-19 cohort, which did not develop myocarditis, likely because of HGF production by inflamed lung tissue." (PMID 41164857, 2025).